PRPH (peripherin)
Description:
Class-III neuronal intermediate filament protein (By similarity). May form an independent structural network without the involvement of other neurofilaments or may cooperate with the neuronal intermediate filament proteins NEFL, NEFH, NEFM and INA to form a filamentous network. Assembly of the neuronal intermediate filaments may be regulated by RAB7A (By similarity). Plays a role in the development of unmyelinated sensory neurons (By similarity). May be involved in axon elongation and axon regeneration after injury (By similarity). Inhibits neurite extension in type II spiral ganglion neurons in the cochlea (By similarity).
Synonyms: NEF4; PRPH1
Tractability: Antibody: its Gene Ontology location is reachable by antibodies, with medium confidence. PROTAC: ubiquitination databases record sites on it.
Gene: Protein-coding gene on chromosome 12 (49,295,147 to 49,298,686, forward strand). Ensembl gene ENSG00000135406.
Subcellular location: Cytoplasm, cytoskeleton; Cell projection, axon; Perikaryon
Gene Ontology:
Molecular function: protein binding; structural constituent of cytoskeleton; structural molecule activity
Biological process: intermediate filament organization
Cellular component: extracellular exosome; membrane; axon; intermediate filament; perikaryon; plasma membrane; type III intermediate filament; cytoskeleton
Genetic constraint (gnomAD): Loss-of-function variants: 48 observed, 52.57 expected, observed/expected ratio (o/e) 0.91, 90% interval 0.72 to 1.16. The upper end of that interval is the gene's LOEUF score, 1.16, which puts it in group 5 of 6, group 1 being the genes least tolerant of losing a copy. Missense variants: 579 observed, 634.54 expected, observed/expected ratio (o/e) 0.91, 90% interval 0.85 to 0.98. Synonymous variants: 279 observed, 293.3 expected, observed/expected ratio (o/e) 0.95, 90% interval 0.86 to 1.05.
Gene-disease validity (ClinGen):
ClinGen rates the evidence that PRPH causes each of these diseases.
amyotrophic lateral sclerosis (autosomal dominant): Limited. Amyotrophic lateral sclerosis (ALS) is a neurodegenerative disease characterized by progressive muscular paralysis reflecting degeneration of motor neurons in the primary motor cortex, corticospinal tracts, brainstem and spinal cord.
Homologues: Orthologues: chimpanzee PRPH (100% identical), macaque PRPH (99% identical), dog PRPH (97% identical), pig PRPH (96% identical), guinea pig PRPH (96% identical), rat Prph (96% identical), mouse Prph (95% identical), rabbit PRPH (81% identical), tropical clawed frog prph (70% identical), zebrafish prph (60% identical). Paralogues in human: DES (58% identical), VIM (57% identical), GFAP (49% identical), INA (46% identical), NEFL (43% identical), NEFM (43% identical), KRT8 (33% identical), KRT5 (33% identical), KRT75 (33% identical), KRT6A (32% identical), KRT6B (32% identical), KRT6C (32% identical), and 56 more.
Diseases named in the same sentence as PRPH in open-access papers:
PRPH is named in the same sentence as 70 diseases in open-access papers, as found by Europe PMC text mining. Sharing a sentence is not in itself a finding about the gene and the disease. The quoted sentences say what the papers report.
amyotrophic lateral sclerosis (10 papers, 2012 to 2025). "One of the initial and pivotal implications of peripherin has been its association with amyotrophic lateral sclerosis (ALS) (Xiao, McLean, and Robertson 2006)." (PMID 39995075, 2025). "Peripherin is mutated in amyotrophic lateral sclerosis (ALS) and a neurotoxic splice variant has been identified in a mouse model of ALS." (PMID 23179371, 2013). "The review also explores peripherin involvement in several neurological disorders, such as Amyotrophic Lateral Sclerosis, where its abnormal expression and aggregation contribute to disease pathology." (PMID 39995075, 2025). "Finally, although the evidence is weak, PRPH has been linked to amyotrophic lateral sclerosis (ALS) (OMIM #170710)." (PMID 30992453, 2019). "Peripherin is mainly expressed in the peripheral nervous system and found in pathological inclusions of patients with amyotrophic lateral sclerosis (ALS)." (PMID 26694421, 2015). "In amyotrophic lateral sclerosis (ALS) patients, peripherin together with neuronal IFs were detected in the majority of abnormal IF inclusion bodies in mature or aging motor neurons." (PMID 22252275, 2012). "In amyotrophic lateral sclerosis (ALS) patients, miR-105 and miR-9 mainly dominate peripherin expression in motor neurons by targeting the 3’UTR of peripheral mRNA; however, their effects on EV71 have not been explored." (PMID 35548469, 2022).
neuroblastoma (6 papers, 2015 to 2025). Neuroblastoma (NB) is the most common solid, extracranial childhood tumor. "To perform our experiments, we used the Neuro2A mouse neuroblastoma cell line known to express peripherin." (PMID 39859265, 2025). "Research conducted on infected mouse cell lines (neurons and neuroblastoma) has revealed the involvement of peripherin in Enterovirus‐A71 (EV‐A71) infection." (PMID 39995075, 2025). "To date, aberrant PRPH methylation has been reported in two studies on liver cancer and neuroblastoma." (PMID 32441866, 2020). "Another example is PRPH (neurofilament 4, 57 kDa), which was found to be down-regulated at both metastatic sites compared to the primary tumors in our neuroblastoma metastasis model." (PMID 30228356, 2018). "Additionally, peripherin demonstrates promise as an immunohistochemistry marker for diagnosing neuroblastoma, with high efficiency in the differential diagnosis of small round cell tumours of childhood." (PMID 39995075, 2025). "A negative effect on peripherin, leading to its aggregation and subsequent cell death, is caused by the interaction with the C1b domain of protein kinase C epsilon (PKCε) in neuroblastoma cells." (PMID 39995075, 2025). "Moreover, embryonic stem cells have been differentiated into sympathetic neurons expressing peripherin, which represents a useful model to study neuroblastoma pathogenesis." (PMID 36499746, 2022). "Furthermore, the RA-induced neuroblastoma differentiation was accompanied by GATA3 downregulation and the upregulation of peripherin, a neuronal differentiation marker." (PMID 25351211, 2015).
diabetes (5 papers, 2007 to 2025). "In sympathetic ganglia, diabetes-induced increases in axon diameter were associated with the accumulation of the type III intermediate filament peripherin, which has recently been demonstrated to be a normal subunit of neurofilaments in peripheral neurons." (PMID 24847201, 2014). "Peripherin gene becomes overexpressed also in pancreatic cancer and a high association has been demonstrated with diabetes mellitus, raising therefore the question of whether an autoimmune mechanism can be the basis of the development of DM related to pancreatic cancer." (PMID 39995075, 2025). "Nevertheless, peripherin in diabetes mellitus seems to play a role not only as an immune target but also as a molecule for neuronal wellness." (PMID 39995075, 2025). "Alterations of its expression or assembly have been found in some neurodegenerative disorders, but peripherin is also involved in diabetes and infectious diseases." (PMID 36499746, 2022). "We also used Western blots to assess if diabetes increased protein expression levels for peripherin and β-tubulin III in the whole tissue." (PMID 24847201, 2014). "The findings suggest that changes in peripherin within the perivascular nerve plexus may provide an early indication of diabetes induced changes in perivascular nerves." (PMID 24847201, 2014). "Therefore, to assess if diabetes might be having a similar effect on sympathetic nerves supplying PMAs, we assessed if there were increases in immunolabeling for peripherin." (PMID 24847201, 2014). "In order to determine whether this decrease of TRPV1-expressing fibres is due solely to the denervation associated with diabetes, the number of TRPV1-immunoreactive fibres was correlated with the number of fibres obtained with the neuronal markers neurofilaments or peripherin." (PMID 17521436, 2007). "A subsequent study has confirmed that phosphorylated peripherin (in dimeric conformation) may be a candidate antigen for diabetes mellitus type I (DM‐I)." (PMID 39995075, 2025). "None of these changes were detected in PMAs from STZ-HI rats, indicating that increased peripherin in sympathetic axons of STZ-LI rats is likely due to hyperglycemia and provides a marker of diabetes-induced nerve damage." (PMID 24847201, 2014). "A diabetes-specific targeted analysis showed negatively enriched Z-disc and contractile gene sets enriched due to the downregulation of CASQ2, peripherin (PRPH), nebulette (NEBL), titin-cap (TCAP), and LIM domain-binding proteins LDB3, PDLIM4, and PDLIM5 (Dataset EV36)." (PMID 40759793, 2025).
retinal degeneration (5 papers, 2012 to 2022). Degeneration of the retina. "In retinal degeneration slow (Rds) mice, retinal degeneration occurs due to mutant peripherin, and the heterozygous model exhibits early-onset progressive rod degeneration." (PMID 36232975, 2022). "The second known targeting sequence resides within the C-terminus of peripherin/retinal degeneration slow (also known as rds or peripherin-2, hereafter referred to as peripherin)." (PMID 23342122, 2013). "This can be seen in other mouse models with photoreceptor specific mutations (such as peripherin and rhodopsin), which do not have an early RPE phenotype despite retinal degeneration." (PMID 33681195, 2021).
neuropathy (4 papers, 2008 to 2025). A disorder affecting the nervous system that manifests with pain, tingling, numbness, and/or muscle weakness. "Abnormal peripherin expression is linked to neurological disorders, including ALS and neuropathy." (PMID 39995075, 2025). "Serum peripherin measurement should also be tested on cohorts of patients with other forms of axonal peripheral nerve disorders such as vasculitis, toxic and chemotherapy-induced neuropathies." (PMID 37435933, 2023). "Since peripherin plays a role not only in neurite outgrowth during development but also in axonal regeneration after injury, these data suggest that the altered interaction between disease-causing RAB7A mutants and peripherin could play an important role in CMT2B neuropathy." (PMID 23179371, 2013). "It was recently demonstrated that many islet-infiltrating B-cells in IDDM produce antibodies that are specific for peripherin and therefore recognize the PNS, which could explain the neuropathy that is commonly seen in IDDM." (PMID 18294400, 2008).
motor neuron diseases (3 papers, 2023 to 2025). "Plasma peripherin (PRPH) levels are significantly elevated in patients with motor neuron diseases (MND), including ALS, compared to both MND mimics and healthy controls." (PMID 40476320, 2025). "The significance of serum peripherin as a clinical biomarker in motor neuron disease will be reviewed later." (PMID 39995075, 2025). "The first and, to date, the only study that has investigated serum and CSF levels of peripherin in patients with motor neuron diseases (MND) was conducted by Sabbatini and colleagues in 2021." (PMID 39995075, 2025).
retinal dystrophies (3 papers, 2013 to 2023). "The peripherin gene (PRPH2) mutation is associated with photoreceptor cell dysfunction as well as in several inherited retinal dystrophies." (PMID 39298723, 2023). "This has occurred in the field of retinal dystrophies where there has been a shift from grouping by somewhat arbitrary pictorial descriptions (e.g. butterfly-shaped macular dystrophy) to defining disease by the gene responsible (e.g. a peripherin/RDS retinal dystrophy)." (PMID 23617902, 2013).
retinitis pigmentosa (3 papers, 2007 to 2022). Retinitis pigmentosa (RP) is an inherited retinal dystrophy leading to progressive loss of the photoreceptors and retinal pigment epithelium and resulting in blindness usually after several decades. "A high frequency (23%) of mutations in the peripherin/RDS gene was found in a cohort of 61 unrelated patients with various types of autosomal dominant central retinal dystrophies as compared with a low prevalence (1.3%) of mutations in this gene causing retinitis pigmentosa in a Spanish population." (PMID 17653047, 2007). "In Prph2 “null” Rds mice, the lack of peripherin downregulates rhodopsin gene expression, causing a gradual loss of rod cells characteristic of macular diseases as retinitis pigmentosa." (PMID 35656327, 2022).
type 1 diabetes (3 papers, 2014 to 2025). "The presence of peripherin antibodies in patients with type 1 diabetes could explain the neuropathy often associated with this disease." (PMID 36499746, 2022). "These antibodies are directed to phosphorylated peripherin, which represents a major humoral antigen in type 1 diabetes." (PMID 36499746, 2022). "This study shows that STZ-induced type I diabetes increased both the thickness of perivascular nerve fibers and the expression of peripherin in the perivascular nerve plexus of PMAs." (PMID 24847201, 2014). "Peripherin antibodies were present in patients with type 1 diabetes, and a reduction in peripherin expression was observed to accompany hyperalgesia in a rat streptozotocin-induced type 1 diabetes model." (PMID 40828619, 2025). "Interestingly, in Sprague–Dawley rats treated with streptozotocin in order to create a rodent model of type 1 diabetes, cutaneous innervation showed decreased expression of peripherin, possibly contributing to hyperalgesia." (PMID 36499746, 2022). "Indeed, a model of peripheral neuritis mediated by peripherin-autoreactive B-lymphocytes was recently established in an NOD (nonobese diabetic) mouse model of type 1 diabetes." (PMID 36499746, 2022).
asthma (2 papers, 2012). "Compared with the peripherin staining detected in control rats, the density of peripherin was higher in s-control rats and the asthmatic rats (vs. control, all P<0.05), and was further enhanced in s-asthmatic rats (vs. asthma, P<0.05)." (PMID 22957086, 2012). "The results suggest that the beneficial effects of KTR in treating asthma are mediated by downregulation of peripherin expression in AMCCs, thus inhibiting the transformation of AMCCs to neurons." (PMID 22474509, 2012). "Furthermore, the results indicated that the number of peripherin-positive ganglion cells were increased in the adrenal medulla of asthmatic rats compared with the control rats (vs. control, P<0.05), and even more in s-asthmatic rats than those in asthmatic rats (vs. asthma, P<0.05)." (PMID 22957086, 2012).
Autoimmunity (2 papers, 2018 to 2025). The occurrence of an immune reaction against the organism's own cells or tissues. "However, it remains unclear if autoimmunity against peripherin is the primary autoimmune target leading to endocrine autoimmune disease." (PMID 39995075, 2025). "Other human diseases characterized by autoimmunity and pain such as rheumatoid arthritis have many identified autoantigens, and in fact, our own experiments suggested that other keratin species, tubulin, alpha-enolase, peripherin, and other proteins may serve as autoantigens." (PMID 29642930, 2018).
chronic inflammatory demyelinating polyradiculoneuropathy (2 papers, 2023 to 2025). A rare neurological disorder in which there is inflammation of nerve roots and peripheral nerves and destruction of the fatty protective covering (myelin sheath) over the nerves. "Peripherin and periaxin, biomarkers of peripheral axonal damage and demyelination, respectively, have recently been validated in Guillain‐Barré syndrome (GBS) and chronic inflammatory demyelinating polyradiculoneuropathy (CIDP)." (PMID 40542608, 2025). "Peripherin and periaxin, biomarkers of peripheral nerve axonal damage and acute demyelination, respectively, have recently been validated in the inflammatory neuropathies Guillain‐Barré syndrome (GBS) and chronic inflammatory demyelinating polyradiculoneuropathy (CIDP)." (PMID 40542608, 2025).
dementia (2 papers, 2023 to 2025). Loss of intellectual abilities interfering with an individual's social and occupational functions. "The high peripherin levels in a small number of patients with multiple sclerosis, dementia and healthy controls were unexpected." (PMID 37435933, 2023). "They found median serum peripherin levels of 5.376 ng/mL in ALS, 5.653 ng/mL in spinal muscular atrophy (SMA), and 10.224 ng/mL in spinal and bulbar muscular atrophy, compared to 3.168 ng/mL in healthy controls, 1.793 ng/mL in dementia, and 2.21 ng/mL in peripheral neuropathy (PN)." (PMID 39995075, 2025).
Hyperglycemia (2 papers, 2014 to 2023). An increased concentration of glucose in the blood. "As no changes in structure of the perivascular nerve plexus or in peripherin protein expression or immunolabeling were observed in PMAs from STZ-HI rats, the effects observed in PMAs from STZ-LI rats were likely due to hyperglycemia and/or to the reduced neurotrophic action of insulin." (PMID 24847201, 2014). "Ten weeks after the onset of hyperglycemia, myenteric whole-mount preparations from the duodenum, ileum and colon of streptozotocin-induced diabetic, insulin-treated diabetic and control rats were prepared for TLR4/peripherin double-labelling fluorescent immunohistochemistry." (PMID 36672637, 2023).
Macular dystrophy (2 papers, 2007 to 2008). Macular dystrophy is a nonspecific term for retinal degeneration, generally confined to the macula, usually presumed of genetic origin. "Perhaps the most difficult macular dystrophy to distinguish from that associated with the A3243G mtDNA mutation, by AF imaging alone, is the maculopathy caused by the dominant R172W peripherin mutation." (PMID 18441172, 2008). "We report the different macular dystrophy phenotypes associated with mutations in the peripherin/RDS gene found in a Spanish population and compare these phenotypes with the associated mutations reported in other populations." (PMID 17653047, 2007). "Different macular dystrophy phenotypes according to the mutations in peripherin/RDS are shown." (PMID 17653047, 2007).
pancreatic cancer (2 papers, 2025). "We examined nerve invasion, a characteristic of patients with pancreatic cancer When stained with peripherin, as a marker of peripheral nerves and GFP, we observed perineural invasion in the PDOTX group but not in the PDOCX group." (PMID 40063301, 2025).
polyneuropathies (2 papers, 2023 to 2025). "Additionally, peripherin has been linked to polyneuropathies, traumatic axonal injury, and diabetic neuropathy, suggesting its broader relevance as a biomarker in these conditions." (PMID 39995075, 2025). "Alterations in proteins interacting with peripherin can cause polyneuropathy." (PMID 39995075, 2025).
adrenal carcinoma (1 paper, 2019). A carcinoma involving a adrenal gland. "To gain understanding of the effect of the two variant isoforms generated from rs73112142-A on the formation and function of peripherin, we overexpressed cDNAs for both isoforms as well as WT PRPH in SW13 cells, a human adrenal carcinoma cell line that lacks IF proteins." (PMID 30992453, 2019).
amyloidosis (1 paper, 2026). A disorder characterized by the localized or diffuse accumulation of amyloid protein in various anatomic sites. "This study aimed to investigate serum levels of NfL, glial fibrillary acidic protein (GFAP), and peripherin (PRPH) in patients with ATTRV30M amyloidosis and pre-symptomatic gene carriers, compared with controls." (PMID 42259879, 2026).
Atrophy (1 paper, 2023). Any weakening or degeneration, especially through lack of use. "Low-level peripherin expression has also been demonstrated in the cerebellum and corticospinal tract of the brainstem, and raised serum levels in such cases may represent CNS damage or atrophy." (PMID 37435933, 2023).